TRPV2 (transient receptor potential cation channel subfamily V member 2)
Diseases named in the same sentence as TRPV2 in open-access papers (continued):
Sharing a sentence is not in itself a finding about the gene and the disease.
breast carcinoma (continued). "Next we confirmed the role of TRPV2 in enhancing DOX-mediated effects by overexpressing TRPV2 in TNBC breast cancer cell line SUM159 and analyzed the drug uptake potential of these cells." (PMID 30323891, 2018). "Antimicrobial peptide LL-37, which is released from infiltrating immune cells, is able to activate TRPV2 and the Ca2+-activated K+ channel (KCa1.1) in different breast cancer cell lines leading to increased migration." (PMID 29772843, 2018). "We confirmed these results by analyzing the correlation of TRPV2 expression in basal breast cancer subtype on RFS using publically available Kaplan Meier plotter." (PMID 30323891, 2018). "Next, we analyzed the correlation of TRPV2 expression to the prognosis of chemotherapy-treated breast cancer patients using Kaplan Meier datasets." (PMID 30323891, 2018). "We analyzed the correlation of TRPV2 expression with the clinical outcome of ERα- breast cancer patients using publically available Kaplan Meier plotter." (PMID 30323891, 2018). "TRPV2 plays an important regulatory role in breast cancer cells." (PMID 40078961, 2025). "The results demonstrate that after local delivery of BG to the solid tumor, US effectively triggers calcium overload by activating the overexpressed TRPV2 channels, leading to mitochondrial autophagy and apoptosis in breast cancer cells, thereby inhibiting tumor growth with high precision." (PMID 40013983, 2025). "Our elucidation of this TRPV2-mediated regulation of autophagy in breast cancer cells provides valuable insights for the development of targeted therapies aimed at manipulating autophagy pathways to control breast cancer progression." (PMID 39334351, 2024). "Likewise, western blot analysis revealed increased expression of ATG, an elevated ratio of LC3-II to LC3-I, and decreased SQSTM1 in breast cancer cells upon TRPV2 activation by cannabidiol." (PMID 39334351, 2024). "Given the pivotal role of TRPV2 as a calcium-permeable cation channel and a crucial modulator of calcium handling, we then investigated the potential role of TRPV2 in mediating extracellular calcium influx in breast cancer." (PMID 39334351, 2024). "Notably, at the 72-hour time point, a reduction in the relative healing area was observed in MCF-7, SK-BR-3, and MDA-MB-231 breast cancer cells transfected with TRPV2 siRNA compared to the control group." (PMID 39334351, 2024). "We next investigated regulatory role of TRPV2 on autophagy in breast cancer." (PMID 39334351, 2024). "Furthermore, the activation of TRPV2 by cannabidiol was found to enhance the proliferative and metastatic potential of breast cancer cells." (PMID 39334351, 2024). "Moreover, our findings shed light on the potential therapeutic implications of TRPV2 in promoting the progressive potential of breast cancer through the modulation of autophagy via calcium signaling." (PMID 39334351, 2024). "In our study, we unveil a novel mechanism by which TRPV2 controls autophagy in breast cancer cells." (PMID 39334351, 2024). "However, this cannabidiol-induced elevation in extracellular Ca2+ influx was reversed in breast cancer cells with TRPV2 knockdown." (PMID 39334351, 2024). "Furthermore, we explored the effects of TRPV2 on breast cancer cell migration using a wound healing assay." (PMID 39334351, 2024). "Moreover, we reveal that TRPV2 facilitates cancer progression by modulating the CaMKKβ/AMPK/ULK1-autophagic axis through mediating calcium influx, providing new insights into TRPV2 as a novel therapeutic target for breast cancer treatment." (PMID 39334351, 2024). "Nevertheless, the role of TRPV2 in breast cancer remains poorly elucidated." (PMID 39334351, 2024). "Therefore, further investigations are warranted to confirm the dependence of the translocation process of TRPV2 in breast cancer cells on PI3K." (PMID 39334351, 2024).
breast carcinoma (continued). "Moreover, other studies have revealed upregulated expression of PI3K in breast cancer cells, further implying its involvement in trafficking of TRPV2 to the plasma membrane." (PMID 39334351, 2024). "Considering the prominent expression of TRPV2 in breast cancer, we investigated whether this correlation is associated with elevated autophagic activity." (PMID 39334351, 2024). "Given the implications of Ca2+/calmodulin-dependent kinase β (CaMKKβ) in autophagy regulation, coupled with its reported modulation by TRP channels, we sought to determine the potential involvement of CaMKKβ in mediating TRPV2-induced autophagy in the context of breast cancer." (PMID 39334351, 2024). "In our study, we utilized cannabidiol, a TRPV2 activator, to treat breast cancer cells." (PMID 39334351, 2024). "We then employed the MTT assay to examine the impact of TRPV2 on breast cancer cell proliferation." (PMID 39334351, 2024). "Moreover, the expression of TRPV2 improves recurrence-free survival in breast cancer patients who have undergone chemotherapy treatment." (PMID 37755210, 2023). "CBD has previously been shown to act through TRPV2 in breast cancer." (PMID 35267489, 2022). "In addition, via activating TRPV2 and PI3/Akt signaling, and then inducing recruitment of TRPV2 from intracellular vesicles to the plasma membrane of pseudopodia, LL-37 promotes proliferation and growth of breast cancer cells." (PMID 36081952, 2022). "Indeed, TRPV2 was first identified as being a growth factor-regulated channel as it mediated IGF-1 induced Ca2+ entry in breast cancer cells." (PMID 34936030, 2021). "However, TRPV2 activation by the antimicrobial peptide LL-37 promoted migration (metastasis) of the highly TRPV2-expressing breast cancer cell line MDA-MB-435 and low TRPV2-expressing MCF-7 and MDA-MB-231 cells." (PMID 33376561, 2020). "Therefore, the therapeutic approach taken for modulating TRPV2 expression should be carefully evaluated to obtain a beneficial outcome for breast cancer patients." (PMID 33376561, 2020). "In addition, higher TRPV2 expression is associated with better prognosis in TNBC/basal and ERα- breast cancer patients especially those who were treated with chemotherapy." (PMID 30323891, 2018). "To investigate whether TRPV2 and LL-37 may be connected in breast cancer, we performed an immunohistochemical study on sections of 101 breast tumors." (PMID 26993604, 2016). "However, the precise mechanism by which TRPV2 regulates autophagy through Ca2+ modulation in breast cancer cells remains unknown." (PMID 39334351, 2024). "Notably, our analysis also revealed a differential expression of TRPV2 in breast cancer cells." (PMID 39334351, 2024). "Furthermore, these results further solidify TRPV2 as a promising candidate for a biomarker that could enhance the accuracy of breast cancer staging." (PMID 39334351, 2024). "In breast cancer cell line MCF-7, Trinilast blocks IGF-1-induced low TRPV2 expression by inhibiting voltage-independent Ca2+ channel-mediated calcium in-flow." (PMID 40078961, 2025). "Our data indicated a decrease in LC3 dots in TRPV2-silenced MCF-7, SK-BR-3, and MDA-MB-231 breast cancer cells." (PMID 39334351, 2024). "In conclusion, our study highlights the high expression of TRPV2, a calcium-permeable TRP channel, in breast cancer, highlighting its potential utility as a biomarker for assessing the malignancy stage." (PMID 39334351, 2024). "Conversely, the high metastatic breast cancer cell line, MDA-MB-231, demonstrated higher expression of TRPV2." (PMID 39334351, 2024). "In contrast, the application of the TRPV2 agonist cannabidiol to MCF-7, SK-BR-3, and MDA-MB-231 breast cancer cells resulted in increased expression of ATG, LC3A, and LC3B, along with reduced SQSTM1, as observed in our quantitative PCR analysis." (PMID 39334351, 2024).
breast carcinoma (continued). "Our results demonstrated that cannabidiol significantly increased both the mRNA level and protein level of TRPV2 in MCF-7, SK-BR-3, and MDA-MB-231 breast cancer cells." (PMID 39334351, 2024). "Quantitative PCR analysis demonstrated a significant reduction in the expression levels of ATG, LC3A, and LC3B, along with an increase in SQSTM1, following TRPV2 knockdown in MCF-7, SK-BR-3, and MDA-MB-231 breast cancer cells." (PMID 39334351, 2024). "Knockdown of TRPV2 in MCF-7, SK-BR-2, and MDA-MB-231 breast cancer cells resulted in diminished cell growth." (PMID 39334351, 2024). "Within this review, we will assess the existing understanding of how five specific TRP channels (TRPA1, TRPC5, TRPV1, TRPV2, and TRPM2) contribute to the resistance of breast cancer to therapeutic interventions." (PMID 37755210, 2023). "The antimicrobial peptide LL-37 promotes the migration of breast cancer cells via PI3K/AKT signaling and increases intracellular Ca2+ levels via Transient Receptor Potential Cation Channel Subfamily V Member 2 (TRPV2)." (PMID 34282767, 2021). "ERα- breast cancer patients who have higher TRPV2 expression and receive chemotherapy treatment show better RFS than those who have lower expression of TRPV2." (PMID 30323891, 2018). "Furthermore, the activation of TRPV2 by cannabidiol exhibited increased proliferation of MCF-7, SK-BR-3, and MDA-MB-231 breast cancer cells, as evidenced by our MTT assay." (PMID 39334351, 2024). "In our study, we observed higher TRPV2 expression in breast cancer cell lines (MCF-7, SK-BR-3, and MDA-MB-231) compared to normal breast cells (MCF-10 A)." (PMID 39334351, 2024). "There was a study that reported that LL-37 binds to ErbB2 receptor and transient receptor potential cation (TRPV2) which led to activation of MAPK signaling and the PI3K/AKT pathway in breast cancer cells and resulted in enhanced cell proliferation, migration, and anchorage-independent growth." (PMID 32365569, 2020). "There are numerous studies showing a clear correlation between cancer patient survival and TRP channel expression, e.g., TRPC1, TRPM2 and TRPV4 in breast cancer, TRPM7 in PDAC, TRPM8 in bladder cancer and osteosarcoma and TRPV2 in breast and esophageal cancer to name just a few examples." (PMID 29772843, 2018). "In summary, our studies show that TRPV2 could be used as a novel biomarker for TNBC and basal-type breast cancer patients." (PMID 30323891, 2018). "Overall, our studies for the first time revealed that TRPV2 might be a good prognostic marker for TNBC and ERβ- breast cancer patient especially for those who are treated with chemotherapy." (PMID 30323891, 2018). "In order to confirm whether the relation between LL-37 and TRPV2 held true on the functional level as well, we performed a migration study on MCF7, and in addition on the high malignant MDA-MB-231 breast cancer cell line." (PMID 26993604, 2016). "In case of ERα+ breast cancer patients, TRPV2 expression level does not affect RFS whether the patients receive chemotherapy or not." (PMID 30323891, 2018). "In contrast, TRPV2 expression level does not affect RFS in ERα+ breast cancer patients." (PMID 30323891, 2018). "However, not much is known about the role of TRPV2 in breast cancer and drug uptake." (PMID 30323891, 2018). "Moreover, as in MM and breast cancer cells, combination of CBD and chemotherapeutic drug, dispays an increased cytotoxic effect compared with chemotherapeutic drug or CBD alone, especially in TRPV2-transfected cells, suggesting that this effect could be partially due to TRPV2 activation by CBD." (PMID 32751388, 2020). "However, we have not found significant correlation between TRPV2 expression and RFS in ERα+ breast cancer patients." (PMID 30323891, 2018).
cardiomyopathy (15 papers, 2006 to 2025). A disease of the heart muscle or myocardium proper. "The TRPV2 channel has been implicated in thermal pain-sensing, muscular dystrophy, and cardiomyopathy, among other diseases." (PMID 38919257, 2024). "These facts suggested that tranilast inhibits TRPV2 in humans and is effective for treating cardiomyopathy associated with muscular dystrophy." (PMID 31394715, 2019). "In this review, we introduce our recent findings and discuss the current progress in the development of TRPV2 inhibitors and their therapeutic applications for cardiomyopathy associated with muscular dystrophy." (PMID 31394715, 2019). "Further, the cardiac-specific overexpression of TRPV2 caused a cardiomyopathy due to cellular Ca2+ overload in a transgenic mouse model." (PMID 16787531, 2006). "In addition, increased surface expression of TRPV2 has been observed and implicated in several diseases, including muscular dystrophy, cardiomyopathy, and cancer." (PMID 24392006, 2013). "Thus, targeting TRPV2 may become a new clinical option to treat cardiomyopathy-associated heart failure." (PMID 26482920, 2016). "While TRPV2 presents as a promising therapeutic target for cardiomyopathy and MD, research on specific inhibitors is currently underway." (PMID 39465141, 2024). "Transient receptor potential vaniloid 2 (TRPV2), a stretch‐sensitive Ca2+‐permeable channel, can accumulate and become activated in the sarcolemma of cardiomyocytes/myocytes in cardiomyopathy and MD." (PMID 39465141, 2024). "In animal models of cardiomyopathy and muscular dystrophy (MD), TRPV2 inhibition was effective against heart failure and motor function." (PMID 35578298, 2022). "Tranilast was effective in hamster models of cardiomyopathy and myocyte degeneration by resulting in the effective removal of TRPV2 from the sarcolemma of DCM hamsters." (PMID 35578298, 2022). "Recent reports have clarified that TRPV2 is concentrated and activated in the sarcolemma of cardiomyocytes/myocytes during cardiomyopathy/heart failure and muscular dystrophy." (PMID 31394715, 2019). "It was revealed that plasma membrane expression of TRPV2 is enhanced and activated in cardiomyopathy, and TRPV2 inhibition decreases plasma membrane localization of TRPV2, abnormal Ca2+ signaling, and muscle degeneration." (PMID 31394715, 2019). "“TRPV2 inhibition therapy” as mentioned here is expected to open up a new therapeutic strategy for muscle dysgeneses, such as cardiomyopathy/heart failure and MD." (PMID 31394715, 2019). "We observed that reducing TRPV2 activity was an effective therapeutic strategy for muscular dystrophy and cardiomyopathy." (PMID 29581825, 2018). "It will be important to use these newly characterized antibodies to determine if the expression and distribution of TRPV2 changes in disease states such as muscular dystrophy, cardiomyopathy and cancer." (PMID 24392006, 2013). "Based on these available tools, TRPV2 has been proposed to play a major functional role in diseases such as muscular dystrophy, cardiomyopathy, prostate cancer, bladder cancer, glioblastoma development and diabetes." (PMID 24392006, 2013). "Several studies in the past few years have also identified a role for TRPV2 in cardiac function, and have suggested that inhibition of TRPV2 activity may be a potential target for the treatment of cardiomyopathy and heart failure." (PMID 35406761, 2022). "The blockade of TRPV2 is likely to yield interesting findings in the treatment and potentially prevention of cardiomyopathy in patients with muscular dystrophy, though as with all TRPV-related studies, it will be crucial to establish the dose and timing of the modulation of the channel." (PMID 34867442, 2021). "Interestingly, TRPV2-mediated Ca2+ overloading was previously reported to contribute to muscular dystrophy and/or cardiomyopathy in humans and animal models." (PMID 24475260, 2014). "The severity of the cardiomyopathy was roughly related to sarcolemmal TRPV2 levels." (PMID 16787531, 2006).
cardiomyopathy (continued). "In the patients of cardiomyopathy as well as in its genetic and chemically induced animal models which typically show ventricular dilation, fibrosis, and severely compromised heart function, the expression of TRPV2 was found to be concentrated on the ventricular sarcolemma." (PMID 26482920, 2016). "Transient receptor potential cation channel, subfamily V, member 2 (TRPV2) is a principal candidate for abnormal Ca2+-entry pathways, which is a potential target for therapy of muscular dystrophy and cardiomyopathy." (PMID 29581825, 2018). "More recent studies have added a new connection of TRP channels (TRPV2 and TRPM4) to cardiomyopathy." (PMID 26482920, 2016). "Although TRPV2 is a potential therapeutic target for cardiomyopathy, there were no TRPV2 inhibitors available until recently." (PMID 31394715, 2019). "Although TRPV2 seems to be an excellent therapeutic target for cardiomyopathy/heart failure and MD, no specific inhibitors have been identified until recently." (PMID 31394715, 2019). "At present, advanced medicine B is promoting “a multicenter joint non-blind single-group study of TRPV2 inhibitors for myocardial injury in muscular dystrophy” for the repositioning of tranilast for human cardiomyopathy." (PMID 31394715, 2019).
gastric cancer (11 papers, 2019 to 2025). A primary or metastatic malignant neoplasm involving the stomach. "As a result, TRPV2 expression is associated with lymphatic invasion, venous invasion and poor prognosis in gastric cancer patients." (PMID 36158191, 2022). "TRPV2 overexpression is also linked to high relapse-free survival in triple-negative breast cancer, where the reverse is found in patients with esophageal squamous cell carcinoma or gastric cancer." (PMID 37892239, 2023). "TRPV2 expression is markedly increased in gastric cancer, where it has been proposed to be a prognostic biomarker, and in prostate cancer, where it is associated with castration resistance and metastatic progression." (PMID 41155636, 2025). "In gastric cancer, high TRPV2 expression correlates with advanced stage and poor prognosis, and mechanistically, TRPV2 confers cisplatin resistance by modulating cisplatin-induced apoptosis." (PMID 41155636, 2025). "The higher expression of TRPV2 in gastric cancer patients has been proposed as a prognostic biomarker and potential therapeutic target." (PMID 37892239, 2023). "In addition, TRPV2 increases gastric cancer cell migration and invasion through the TGFβ signaling pathway." (PMID 36158191, 2022). "Also, TRPV2 overexpression confers a drug-resistant phenotype in gastric cancer, suggesting that promoting tumor cell apoptosis by targeting TRPV2 may be a potential treatment for overcoming drug resistance." (PMID 35140788, 2022). "Our analyses suggest for the first time that the TRPV2 Ca2+ channel predicts the prognosis of gastric cancer patients, even in those with intestinal type GC." (PMID 31083561, 2019).